TRIO (trio Rho guanine nucleotide exchange factor)
Diseases named in the same sentence as TRIO in open-access papers (continued):
Sharing a sentence is not in itself a finding about the gene and the disease.
cancer (16 papers, 2013 to 2025). A tumor composed of atypical neoplastic, often pleomorphic cells that invade other tissues. "Others, such as TRIO, are less well-studied but have previously appeared in the literature and databases of cancer driving genes." (PMID 38721669, 2024). "We found that circ-TRIO is highly expressed in cancer tissues and metastatic cell lines and is correlated with the recurrence and prognoses of TNBC patients." (PMID 36075896, 2022). "TRIO plays a role in cell proliferation and progression of cancer, wherein higher protein expression has been shown to be associated with worse outcome (OS)." (PMID 32133296, 2020). "IPA analysis of these unique up-regulated genes indicated that some genes were associated with cell transformation during cancer progression (ABL1, TRIO, FOSB, NRCAM, TRIB2 and CDK6) and others with cell survival (e.g., BCL10, BBC3, FGF8, HSPA4 and SOD1)." (PMID 29137349, 2017). "TRIO, which is a triple functional domain protein, harbors 2 GEF domains and a protein serine kinase domain and has been implicated in multiple processes of cancer in recent years." (PMID 36075896, 2022). "Based on previous studies, circRNAs can confer progression abilities to cancer cells and perform special regulatory functions in cancer proliferation, migration, and invasion processes; thus, functional experiments of circ-TRIO were also performed by in vitro and in vivo assays." (PMID 36075896, 2022). "Since K69 and K285 residues are known regulatory switches for DVL-1 nuclear localization, we wanted to determine whether these K-residues on DVL-1 also influence transcript levels of DVL-1 target genes such as TRIO, COL5A1 and EXD3 implicated in cancer." (PMID 34659647, 2021). "Using the ChIP Seq bam files, we visualized the exact genomic location of DVL-1 binding (blue peak) at various cancer-associated genes not previously designated as Wnt target genes such as TRIO, COL5A1, EXD3, OR4A47, GLDN, and EFCAB6 compared to IgG control (red peak) using IGV." (PMID 34659647, 2021). "For example, EAS-specific unambiguous probes (n = 484) from the HM450K array were overlapped with promoters and gene bodies of 140 cancer driver genes, such as CTNNB1, DSP, FRK, HLA-A, NOX4, and TRIO." (PMID 40445831, 2025). "Amplification of TRIO and COMMD5 proteins has also been reported in various types of cancer, suggesting an oncogenic function." (PMID 34772375, 2021). "The Cancer Genome Atlas (TCGA) data analysis indicated that the gene expression of TRIO, NET1, ECT2, TIAM2, FARP1, ARHGEF12 and BCR in primary cancer was significantly higher than those in normal tissues." (PMID 32029704, 2020). "Several investigators have previously reported the relevance of TRIO, NET1, ECT2 and TIAM2 in cancer metastasis and clinical prognosis." (PMID 32029704, 2020). "However, the correlation between NAV1, TRIO, and cancer has not been well investigated." (PMID 36979179, 2023).
neurodevelopmental disorder (9 papers, 2019 to 2026). A behavioral and cognitive disorder with onset during the developmental period that involves impaired or aberrant development of intellectual, motor, or social functions. "TRIO encodes a Rho guanine nucleotide exchange factor (RhoGEF) disruptions of which have previously been identified as causal for neurodevelopmental disorders, with domain-specific symptoms." (PMID 40836029, 2026). "Function-damaging variants in the TRIO gene are known to be enriched in individuals with neurodevelopmental disorders (NDDs)." (PMID 35963430, 2022). "De novo mutations and ultra-rare variants in TRIO are enriched in neurodevelopmental disorders (NDDs) and the pattern of these variants differs in different disorders." (PMID 35963430, 2022). "Damaging variants in TRIO have been associated with moderate to severe neurodevelopmental disorders in humans." (PMID 33167890, 2020). "ARID1A and TRIO were already associated with neurodevelopmental disorder, and the missense mutations in these genes were selected as potential causal variants in proband 18 and 19, respectively." (PMID 29463886, 2019). "Variants in TRIO are associated with neurodevelopmental disorders." (PMID 40581118, 2025). "Importantly, different mutations in TRIO have been strongly linked to distinct neurodevelopmental disorders." (PMID 40488454, 2025). "A total of six de novo missense variants were located in genes previously identified as causal for a neurodevelopmental disorder, of which three variants in PRPF8, TRIO and ZBTB7A were classified as likely pathogenic." (PMID 40836029, 2026). "Replication in a person who stutters is required to confirm that stuttering is a feature of the monogenic neurodevelopmental disorders associated with mutations in SPTBN1, PRPF8, TRIO, and ZBTB7A, and to causally link FLT3 and IREB2 to neurodevelopmental disorders." (PMID 40836029, 2026). "A series of single-point variants in the unique β3-β4 loop of TRIO PH2 has been identified in patients with neurodevelopmental disorders (NDDs), but how they impact TRIO GEF2 activity is not known." (PMID 40581118, 2025). "A significant number of these genes (CHD3, SETD1A, KAT6A, SETBP1, TNRC6B, ZFHX4, ARID1A and TRIO) have been associated with neurodevelopmental disorders with or without speech problems." (PMID 29463886, 2019). "Exome sequencing analysis yielded a pathogenic variant in SPTBN1 as well as likely pathogenic variants in PRPF8, TRIO, and ZBTB7A - four genes previously implicated in neurodevelopmental disorders with or without speech problems." (PMID 40836029, 2026). "According to prior literature on the genes implicated by our de novo analyses, none of the patients with neurodevelopmental disorders caused by mutations in SPTBN1, PRPF8, TRIO, and ZBTB7A have been described to stutter." (PMID 40836029, 2026).
infection (6 papers, 2012 to 2025). The state of being infected such as from the introduction of a foreign agent such as serum, vaccine, antigenic substance or organism. "We show that this vaccine can elicit strong anti-TRIO antibody responses, but these antibodies only result in a modest decrease in infection." (PMID 39878467, 2025). "Echo30 infection activates TRIO-guanine nucleotide exchange factor (GEF) domains (GEFD2) and RhoA signaling in turn." (PMID 22586486, 2012). "To elucidate the role of TRIO proteins involved in neuronal cell death induced by Echo30 infection, we determined TRIO protein expression level using immunoblot analysis." (PMID 22586486, 2012). "Our results provide evidence that the role of TRIO protein level increases in neuronal cells due to Echo30 infection." (PMID 22586486, 2012). "Echo30 infection leads to enhanced TRIO protein level, resulting in RhoA and RhoA targeted signaling activation, and contributing to SK-N-SH cell death." (PMID 22586486, 2012). "Our finding shows that TRIO plays a critical role in neuronal cell death by Echo30 infection." (PMID 22586486, 2012). "Interestingly, Echo30 infection to the neuronal cells increases the protein expression of the TRIO." (PMID 22586486, 2012).
neurological disorders (1 paper, 2020). "We therefore propose that TRIO-associated pathologies cover different neurological disorders depending on the mutation location." (PMID 32109419, 2020).
TRIO also shares sentences with these, for which no sentence is quoted: bipolar disorder (2 papers); epilepsy (2); Aortic valve disease (1); attention deficit-hyperactivity disorder (1); breast tumors (1); Choreoathetosis (1); cystic kidney disease (1); deafness autosomal dominant 10 (1); deafness autosomal recessive 28 (1); depressive disorder (1); encephalitis (1); genetic disorder (1); hereditary spastic paraplegia (1); Hip dysplasia (1); holoprosencephaly 9 (1); hypothyroidism (1); language disorder (1); liver (1); movement disorder (1); Neonatal respiratory distress (1); Primary microcephaly (1); promyelocytic leukemia (1); prostate carcinoma (1); Smith-Magenis syndrome (1); soft tissue sarcoma (1); tuberous sclerosis (1); Visual impairment (1).